SPARC (secreted protein acidic and cysteine rich)
Diseases named in the same sentence as SPARC in open-access papers (continued):
Sharing a sentence is not in itself a finding about the gene and the disease.
Insulin resistance (26 papers, 2013 to 2025). Increased resistance towards insulin, that is, diminished effectiveness of insulin in reducing blood glucose levels. "Elevated plasma level of SPARC have shown to be strongly associated with insulin resistance, dyslipidemia and inflammation." (PMID 34777249, 2021). "SPARC is also linked to hyperglycemia and insulin resistance." (PMID 40243151, 2025). "Therefore, our findings implicate a potential role of SPARC in the pathophysiology of insulin resistance in GDM and provide insights on both risk stratification and modification in this patient population." (PMID 24349098, 2013). "Taken together, the association of SPARC and insulin resistance may be mediated by dysfunction of adipose tissue and related dyslipidemia." (PMID 24349098, 2013). "Therefore, SPARC deficiency would reduce insulin secretion (independently of insulin resistance)." (PMID 35208200, 2022). "Moreover, increased SPARC expression in adipose tissue is associated with insulin resistance." (PMID 24349098, 2013). "In this way, glucose uptake of skeletal muscle and glucose tolerance are improved by SPARC treatment which has also been shown to prevent the development of insulin resistance in mice." (PMID 39872377, 2024). "The expression of SPARC is downregulated in granulosa cells obtained from PCOS patients with insulin resistance when compared to normal controls." (PMID 37158892, 2023). "The degree of the expression level of SPARC protein can improve insulin resistance of adipocytes, thereby improving the insulin sensitivity of GK rats." (PMID 37577749, 2023). "Conversely, recombinant SPARC treatment of adipocytes reduced AKT phosphorylation, which is consistent with a prior report that SPARC overexpression induced insulin-resistance in the 3T3L1 adipocyte cell line." (PMID 37781916, 2023). "This recent study showed that SPARC independently represented insulin resistance in late pregnancy, suggesting its possible role in the pathophysiology of GDM." (PMID 34007846, 2021). "Adipose tissue is a major source of SPARC, which in turn inhibits adipogenesis and induces insulin resistance in adipose tissue in an autocrine or paracrine fashion." (PMID 33067534, 2020). "Overexpression of SPARC modulates the expression levels of various pro-inflammatory cytokines, critically involved in insulin resistance, glucose and lipid metabolism during adipogenesis." (PMID 33192583, 2020). "SPARC has been shown to be involved in oxidative stress, neurogenesis, insulin resistance, glucose metabolism and Glut4 expression." (PMID 33067534, 2020). "SPARC suppresses adipogenesis and promotes insulin resistance." (PMID 37577749, 2023). "Dysregulation of SPARC alters the levels of inflammatory cytokines related to insulin-stimulated glucose transport, glucose transporter 4, and ATP synthesis in mitochondria, and eventually induces insulin resistance." (PMID 34751020, 2022). "High SPARC expression in adipose tissue leads to insulin resistance." (PMID 34007846, 2021). "SPARC secreted from adipose tissue could induce ectopic lipid deposition and insulin resistance, whereas SPARC secreted from pancreatic stellate cells mediates the communication between stromal cells and endocrine cells by regulating β-cell survival." (PMID 33817571, 2021). "Furthermore, we show that the LPL and SPARC promoters are enriched for Sp1 and O-GlcNAc modified proteins during insulin resistance in adipocytes." (PMID 25657638, 2014). "SPARC levels are correlated significantly with inflammation and may also be correlated with dyslipidemia and represent an independent determinant of insulin resistance in late pregnancy, indicating a potential role of SPARC in the pathophysiology of GDM." (PMID 24349098, 2013). "The influence of SPARC in insulin resistance and type 2 diabetes may arise from its role in the regulation of collagen assembly and ECM remodelling." (PMID 23840838, 2013).
Insulin resistance (continued). "Having demonstrated that GDM is characterized by elevated level of SPARC, which in turn related to insulin resistance, we next queried whether the relationship between SPARC and insulin resistance is independent of the other metabolic parameters." (PMID 24349098, 2013). "Importantly, the key finding of the current study was the demonstration that SPARC in pregnancy was an independent indicator of insulin resistance." (PMID 24349098, 2013). "We suggest that these data point towards a previously uncharacterised potential role for SPARC in moderation of insulin secretion, separate from the anti-proliferative and profibrotic function of this protein in adipose tissue where it appears to be a moderator of insulin resistance." (PMID 23840838, 2013). "A proinflammatory environment up-regulates expression of SPARC which then promotes the synthesis of ECM components and drives adipose tissue fibrosis and subsequent insulin resistance." (PMID 24349098, 2013). "In our study, we first determined circulating levels of SPARC in pregnant women and found that SPARC levels were elevated significantly in GDM group compared with NGT group and correlated significantly with insulin resistance." (PMID 24349098, 2013). "In previous studies, the relative expression of SPARC in the type 2 diabetes T2DM mice was higher than that in the control mice, and this might be the result of SPARC promoting insulin resistance." (PMID 36755916, 2023). "The co-existence of high SPARC level and elevated inflammation markers in GDM and their close relevance with each other and with insulin resistance suggest that their interaction may play an important role in the development and progression of GDM." (PMID 24349098, 2013). "Therefore, we did not use this method in the evaluation of insulin resistance in our study, but we used multiple simple indices including HOMA-IR, fasting proinsulin and ISIOGTT, which consistently shown the correlation between SPARC and insulin resistance." (PMID 24349098, 2013).
lymph node metastasis (26 papers, 2004 to 2025). "One of the populations is associated with TGFβ-responsive genes, such as periostin, stromelyin-3 (MMP11), and collagen I and secreted protein acidic and cysteine-rich (SPARC), associated with lymph node metastases." (PMID 37046676, 2023). "In esophageal and gastric tumors, high SPARC is associated with lymph node metastases and worse clinical outcome." (PMID 22016635, 2011). "Higher expression of SPARC was significantly associated with lymph node metastasis (P<0.001), lymphatic invasion (P=0.004) and perineural invasion (P=0.047)." (PMID 15558074, 2004). "In addition, for overall survival, high SPARC expression (HR=1.90, 95%CI: 1.14-3.16, P=0.014), large tumor size (P=0.039) and lymph node metastasis (P=0.001) were independent risk factors." (PMID 27421134, 2016). "Further, higher SPARC expression also predicted a better prognosis in patients with lymph node metastasis, as well as in Her2+ patients (N = 60)." (PMID 36157225, 2022). "In another study, SPARC had a dual functional role as a prognosis predictor and potential marker for lymph node metastasis in patients with resected lesions." (PMID 35477379, 2022). "A correlation test found that macrophage SPARC expression was negatively correlated with lymph node metastasis (P =0.017)." (PMID 32226513, 2020). "Univariate analysis using COX proportional hazard (PH) models showed that advanced T stage, presence of lymph node metastasis, and high SPARC expression significantly predicted reduced OS (P = 0.007, 0.001, and 0.024, respectively)." (PMID 28053291, 2016). "In 54 GC patients who underwent preoperative chemotherapy (group A), high SPARC expression after chemotherapy correlated with depth of invasion, lymph node metastasis, and TNM stage (P<0.05)." (PMID 25859409, 2015). "Especially, high levels of SPARC often correlated with the lymph node metastasis, enhanced invasion, metastasis, and poor prognosis, for example, metastasis to the colon, lung, esophagus and pancreas." (PMID 22321704, 2012). "In breast cancer, SPARC was found to be present in higher quantities than normal breast tissue and correlated with lymph node metastases, tumor grade, and 10-year survival." (PMID 22016635, 2011). "The expression of SPARC is correlated significantly with MMP2 mRNA expression in esophageal tumor tissue specimens, and high SPARC expression was found to be correlated significantly with lymph node metastasis and poor patient prognosis." (PMID 21152079, 2010). "We further found that SPARC expression was elevated in lymph node metastasis." (PMID 39382748, 2024). "Furthermore, high SPARC expression was positively correlated with factors such as poor differentiation, advanced stages, and lymph node metastasis in cervical cancer, and served as an unfavorable prognostic marker." (PMID 38914827, 2024). "Lower expression of SPARC correlated with lymph node metastasis (p < 0.001)." (PMID 36157225, 2022). "A correlation test found that macrophage SPARC expression was negatively correlated with lymph node metastasis, which suggested that macrophage-derived SPARC may be a protective factor." (PMID 32226513, 2020). "In multivariable analysis, high SPARC expression (HR=1.73, 95% CI: 1.10-2.73, P=0.018), large tumor size (P=0.012), lymph node metastasis (P=0.002), vascular invasion (P=0.040), and chemotherapy without paclitaxel (PTX) (P=0.018) were independently predictive for DFS in all patients." (PMID 27421134, 2016). "Macrophage SPARC expression was negatively correlated with T staging, TNM staging, number of lymph node metastases, tumour location, and lymph node metastasis." (PMID 32226513, 2020). "SPARC, VCAM1 and ANGPTL4 were found positively correlated with the potentials of lung metastasis, while ITGA1 had a positive relation to lymph node metastasis of enterocoelia." (PMID 26459277, 2015).
lymph node metastasis (continued). "Univariate analysis showed that expression of SPARC, neutrophil-lymphocyte ratio (NLR), tumor diameter, lymph node metastasis, portal vein tumor thrombosis, as well as BCLC and TNM staging exhibited a correlation with the OS of patients with HCC undergone TACE (p < 0.05)." (PMID 32670867, 2020). "Backward stepwise logistic regression analysis was performed for six factors (age, ER, PgR, HER2, lymph node metastasis, and SPARC) in 52 patients (two with no SPARC and histological assessments were excluded)." (PMID 28050738, 2017). "Indeed, the protein levels of SPARC, ANGPTL4 and VCAM1 were remarkably correlated with the potentials of lung metastasis, while ITGA1 was positively related to celiac lymph node metastasis (p < 0.01)." (PMID 26459277, 2015). "The positive rate of SPARC expression in NSCLC with lymph node metastasis was significantly higher than that without lymph node metastasis (81.3% vs 58.5%, P < 0.05)." (PMID 23249717, 2012). "Clinicopathological parameters including lymph node metastasis, lymphocytic infiltration in the tumor interstitial, depth of invasion, distant metastasis, TNM staging, may effect on the prognosis of patients, the expression of SPARC and VEGF, and MVD value, with multivariable models." (PMID 20565704, 2010). "Subtype, lymph node metastasis, tumor size, and NG, Ki67, NLR, PLR, and SPARC/PD-L1 expression were not significant factors." (PMID 36609911, 2023).
diabetes (24 papers, 2013 to 2025). "To further investigate the mechanisms underlying the amelioration of diabetes by SPARC, we conducted cell therapy in STZ-induced diabetic mice." (PMID 41185072, 2025). "Diabetes-associated mesenteric vascular hypertrophy is relevant to increased SPARC expression in vessel walls." (PMID 37577749, 2023). "SPARC deficiency inhibits the rise in superoxide production elicited by diabetes stimulation, avoiding the induced hepatocyte damage." (PMID 37577749, 2023). "SPARC deficiency suppresses diabetes-stimulated increases in superoxide production and eliminates prominent features of hepatocyte damage, such as impaired cytoprotection, inflammation, apoptosis, and autophagy." (PMID 35721704, 2022). "SPARC has been implicated in the pathogenesis of diabetes and is also known to have a potential role in fibrosis, a common consequence of multiple conditions including hypertension." (PMID 31891604, 2019). "The STZ-induced onset of diabetes-related kidney growth is associated with reduction of SPARC protein expression." (PMID 26110898, 2015). "To conclude, we report that the SPARC gene is expressed at detectable levels in human primary islets, and is associated with diabetes status and glucose stimulated insulin secretion in this tissue." (PMID 23840838, 2013). "In the pathogenesis of diabetes-associated renal growth, SPARC is involved in its pathogenesis." (PMID 37577749, 2023). "Consistent with our result, it is reported that the SPARC levels were decreased in islets with diabetes and SPARC deficiency could lead to DM in SPARC null mice." (PMID 36463101, 2022). "We suggest that the association of SPARC with its interacting protein partners may be linked to inflammatory responses underlying STZ-induced diabetes." (PMID 26110898, 2015). "Therefore, we speculate that SPARC at the onset of diabetes may be associated with regulation of Tgfb1 as well as Tgfb1-mediated TNFα production." (PMID 26110898, 2015). "In this study, we established canines and mice models of streptozotocin (STZ)-induced diabetes and administered SPARC-modified MSCs intravenously to assess their therapeutic effects." (PMID 41185072, 2025). "Several studies demonstrated that SPARC is an important player in the context of obesity, diabetes, and fatty liver disease including advanced hepatic fibrosis." (PMID 37834291, 2023). "Functional nanomaterials manipulate SPARC to treat diabetes, which will definitely become a hot topic in the future." (PMID 37577749, 2023). "SPARC identifies novel regulators of islet survival and ß-cell growth, a new target for treating diabetes." (PMID 37577749, 2023). "The occurrence of diabetes-related kidney growth was related to the reduction of mRNA and protein of SPARC." (PMID 37577749, 2023). "SPARC KO mice presented impaired glucose homeostasis and insulin section capacity and SPARC was confirmed as a key factor in the pathogenesis of diabetes." (PMID 35721704, 2022). "Serum SPARC levels also correlate with coronary artery lesion severity in type 2 diabetic patients with coronary heart disease, and newly diagnosed type 2 diabetes mellitus patients also have high plasma SPARC levels." (PMID 34827687, 2021). "In this study, we investigated the tissue-specific expression of SPARC in streptozotocin (STZ)-induced diabetes, and found that SPARC was significantly up-regulated in the liver while down-regulated in the pancreas of STZ-induced diabetic rats." (PMID 26110898, 2015). "In fact, C/EBPβ is negatively modulated by SPARC during adipocyte differentiation, which suggests that up-regulated SPARC correlated with reduced expression of C/EBPβ in the STZ-induced diabetic liver." (PMID 26110898, 2015). "Further, SPARC-knockout mice are protected from type 2 diabetes mellitus (T2DM) and its complications, supporting a role for SPARC in causing T2DM." (PMID 26110898, 2015).
diabetes (continued). "SPARC was expressed at lower levels in primary islet samples from donors with diabetes compared with those from control donors." (PMID 23840838, 2013). "We therefore aimed to characterise the effect of SPARC on beta-cell function and features of diabetes." (PMID 23840838, 2013). "The mean expression levels of SPARC relative to the endogenous control genes was found to be 1.19 in control islets, compared with 0.43 in the islets from subjects with diabetes; p = 0.049." (PMID 23840838, 2013). "Consequently, the present study aims to investigate the therapeutic effects of SPARC-modified MSCs using canines and mice animal models of diabetes that have undergone STZ injury." (PMID 41185072, 2025). "SPARC dramatically exacerbates diabetes in mice fed a high-fat diet." (PMID 37577749, 2023). "The role of SPOCKs in diabetes is unknown but, as for SPARC, high expression of SPOCK-1 in the desmoplastic stroma of PDAC has been associated with poor prognosis." (PMID 27886258, 2016). "Impaired cytoprotective machinery and tissue-specific preservation of stress and inflammation may explain the depleted levels of SPARC in the STZ-induced diabetic pancreas." (PMID 26110898, 2015). "Upon diabetes induction, SPARC might play distinct roles in hepatic and pancreatic tissues in terms of tissue remodelling, fibrogenesis, inflammation, apoptosis, and cytoprotective machinery." (PMID 26110898, 2015). "Interestingly, APC2 as another partner protein of SPARC was strikingly up-regulated in the STZ-induced diabetic pancreas." (PMID 26110898, 2015). "SPARC was expressed at measurable levels in human islets, adipose tissue, liver and skeletal muscle, and demonstrated reduced expression in primary islets from subjects with diabetes compared with controls (p< = 0.05)." (PMID 23840838, 2013). "Also, SPARC is also closely related to diabetes, glucose metabolism, and fat metabolism." (PMID 33584170, 2020). "We observed enrichment in disease ontologies relating to acquired metabolic disease, glucose metabolism disease, diabetes mellitus, carbohydrate metabolism disease, disease of metabolism, and clustering around genes including CXCL5, EGF, and SPARC." (PMID 36138412, 2022). "Therefore, C/EBPβ may play a crucial role in SPARC expression in STZ-induced diabetes." (PMID 26110898, 2015). "In contrast, increased expression of SPARC has been observed in mesenteric vessels of STZ-induced diabetic rats, suggesting pathological significance in the development of vascular remodelling in diabetes." (PMID 26110898, 2015). "SPARC circulating levels are associated with HOMA-IR and HbA1c in obese individuals without diabetes and secretion from adipose tissue is induced by insulin." (PMID 23840838, 2013). "Whilst donors with diabetes had a higher BMI than control donors, no significant increase of SPARC expression due to increased BMI was noted in our samples." (PMID 23840838, 2013). "In addition, the absence of SPARC worsens high-fat diet-induced diabetes in mice." (PMID 37834291, 2023). "This may oppose the role of SPARC in adipose tissue where it is thought to increase fibrosis by increased deposition of insoluble collagen fibers, in contrast islets of patients with diabetes are not characterised by collagen deposition but an accumulation of amyloid (Clark A, 2001)." (PMID 23840838, 2013).